MMP9 (matrix metallopeptidase 9)
Diseases named in the same sentence as MMP9 in open-access papers (continued):
Sharing a sentence is not in itself a finding about the gene and the disease.
heart disease (23 papers, 2012 to 2024). "In our study sample, when performing subgroup analysis, MMP‐9 levels were an independent predictor of survival in patients with underlying cardiac disease." (PMID 31932967, 2021). "The prognostic significance of (early) TIMP‐1 levels has been extended to a heterogeneous group of critically ill patients and further support the predictive value of MMP‐9 levels on short-term mortality, especially in patients with underlying cardiac disease." (PMID 31932967, 2021). "In patients with underlying cardiac diseases, MMP‐9 (p = 0.002) and TIMP‐1 (p = 0.01) were independent predictors of survival (Cox regression)." (PMID 31932967, 2021). "In a logistic regression model, MMP‐9 was independently associated with 30-day survival in the subpopulation of patients with cardiac disease (p = 0.042)." (PMID 31932967, 2021). "In the context of cardiac disease, mir323 has been associated with cardiac exosomal fractions that bind to matrix metalloprotease 9 (MMP9) and downregulate its expression to mitigate MMP9 induced extracellular matrix remodeling." (PMID 33042024, 2020). "It is well-known that an increase of Mmp9 expression is related to heart disease, particularly myocardium ischemia caused by coronary occlusion and resulting in cardiac cell starvation and injury." (PMID 33061247, 2020). "Increasing Mmp9 expression in cardiac fibroblasts is a clinically detrimental sign as it is associated with matrix changes caused by heart disease." (PMID 33061247, 2020). "Univariate analyses revealed that increasing age, male sex and heart disease as well as increasing levels of MMP-9 and MMP-9/TIMP-1 ratio were associated with an increased risk for death, expressed as Hazard Ratio (HR, 95% CI)." (PMID 29650051, 2018). "In heart disease, the administration of IL-10 was shown to result in a significant suppression of proinflammatory cytokine synthesis, MMP-9 activity, and the infiltration of inflammatory cells in the myocardium, leading to a reduction in cardiac fibrosis." (PMID 38792896, 2024). "EGFR and MMP-9 contribute to neointimal proliferation in SP shunts of children with complex cyanotic heart disease." (PMID 36867212, 2023). "Numerous scientific reports confirm that MMP2 and MMP9 have been recognized to play an important role in matrix remodeling in these cardiac disease states." (PMID 35885988, 2022). "For the research of cardiac remodeling, in addition to the H9c2 cell line, the effect of PNG-3 and GsRb1 can be tested using cardiac fibroblasts, another important MMP-9 producer in cardiac diseases." (PMID 36432152, 2022). "Other study indicated that MMP-2 and MMP-9 levels peaks in plasma from patients clinically asymptomatic with an abnormal ECG (an early indicator of cardiac disease) and progressively augmented in patients with advancing Chagas cardiomyopathy." (PMID 29375564, 2017). "Research has shown that MMP-9 can participate in the development of various heart diseases." (PMID 38643140, 2024). "The MMP‐9 and TIMP‐1 levels are significantly elevated in acute critical care settings with increased short-term mortality risk, especially in patients with underlying heart disease." (PMID 31932967, 2021). "In non-COPD, male sex, age, burden of smoking, heart disease and MMP-9/TIMP-1 ratio were associated with increased risk for death, while increased TIMP-1 was protective." (PMID 29650051, 2018). "In non-COPD, male sex, burden of smoking, heart disease and MMP-9/TIMP-1 ratio increased the risk for death, and serum concentration of TIMP-1 had a protective effect." (PMID 29650051, 2018). "Although MMPs are strongly associated with several inflammatory diseases, the data suggested that MMP-2 and MMP-9 plasmatic levels could be used as early biomarkers of cardiac disease." (PMID 29375564, 2017). "The participation of MMP-2 and MMP-9 in several heart diseases has been well established." (PMID 28118356, 2017). "MMP-2 and MMP-9 are known to play key roles in various cardiac disease conditions." (PMID 25822525, 2015).
heart disease (continued). "In a subgroup analysis, plasma MMP‐9 (p = 0.002) and TIMP‐1 (p = 0.01) levels upon admission to the ICU as well as SAPSII (p < 0.0001) were independent predictors for 30-day survival in the patient group with cardiac disease only." (PMID 31932967, 2021). "This can probably be explained by our data showing that these particular patients had significantly higher levels of MMP-9, and is consistent with previous studies in no-RA populations showing higher levels of MMP-9 in heart disease." (PMID 23031278, 2012).
brain diseases (21 papers, 2010 to 2025). "Nevertheless, analyses presented in the publication clearly show a broad pathological role of the MMP-9-1562C/T polymorphism in the human brain disorders." (PMID 37206663, 2023). "Among MMPs, MMP-9 expression and activation play a critical role not only in tissue remodeling but also in the pathogenesis of brain diseases, such as being a risk factor in the integrity of the BBB." (PMID 38203454, 2023). "In consequence, the MMP-9-1562C/T polymorphism influences the likelihood of development and the course of many brain diseases associated with abnormal MMP-9 expression found by many researchers." (PMID 37206663, 2023). "The article describes the single nucleotide polymorphism of the MMP-9-1562C/T gene (rs3918242) and its links to brain disorders." (PMID 37206663, 2023). "MMP-9 expression and activation play a critical role in tissue remodeling associated with the pathogenesis of brain diseases." (PMID 23176293, 2012). "The presence of the allele T often increases the activity of the MMP-9 gene promoter and consequently the expression of MMP-9 when compared to the allele C. This leads to a change in the likelihood of an occurrence of diseases and modifies the course of certain brain diseases in humans." (PMID 37206663, 2023). "Several studies have demonstrated that MMP-9 may participate in several brain injuries and induce the pathogenic process of brain diseases." (PMID 35740292, 2022). "Several studies have indicated that upregulation of MMP-9 may contribute to the pathogenic process of brain diseases by several brain injuries." (PMID 34440126, 2021). "Among MMPs, regulation of MMP-9 plays a critical role in physiological and pathological events, including neuronal precursor migration and apoptosis in the developing cerebellum or in pathogenic processes of brain diseases." (PMID 34440126, 2021). "Several lines of evidence have showed that upregulation of MMP-9 may contribute to the pathogenic process of brain diseases by several brain injuries." (PMID 32505192, 2020). "The primary mechanism of action of MMP9 in brain disorders appears to be its involvement in host defense, as well as its contribution to blood-brain barrier disruption." (PMID 37139237, 2023). "MMP-9 particularly plays an important role in tissue remodeling and in the pathogenesis of brain diseases." (PMID 35740292, 2022). "MMP9, which is involved in many inflammatory processes, is related to the development of many brain diseases, the remarkable increase of which indicated abnormal cerebral changes in maternal PH rat offspring in the present study." (PMID 35115938, 2021). "Among MMPs, MMP-9 expression and activation play a critical role in tissue remodeling in the pathogenesis of brain diseases." (PMID 32505192, 2020). "MMP-9 belongs to a family of extracellular proteases, normally expressed at low levels but substantially overexpressed in many brain diseases." (PMID 31461951, 2019). "Matrix metalloproteinase (MMP)-9, one member of MMPs, has been shown to contribute to the pathology of these brain diseases." (PMID 31905967, 2019). "Matrix metallopeptidase 9 is a major protein related to brain disorders and the BBB." (PMID 36003963, 2022). "Studies thus far have demonstrated that MMP-9 is substantially overexpressed in many brain diseases, which acts as not only a proteolytic enzyme involved in the disruption of the blood–brain barrier (BBB), but also an inflammatory mediator playing an important role in neuroinflammation." (PMID 31461951, 2019). "Up-regulation of MMP-9 has been induced by various brain injuries, which may participate in the pathogenesis of brain diseases." (PMID 23176293, 2012). "Among members of the MMP family, MMP-9 has been shown to be elevated in various brain disorders." (PMID 21134288, 2010).
brain diseases (continued). "The MMP-9-1562C/T polymorphism may result in a change of the MMP-9 mRNA level, and can influence the possibility of an occurrence of diseases, as well as the course of the MMP-9 dependent brain disorders in humans." (PMID 37206663, 2023).
cerebral artery (21 papers, 2014 to 2026). "In a mouse model of middle cerebral artery occlusion, inhibition of MMP-9 expression resulted in increased ZO-1 and occludin expression and reduced BBB permeability." (PMID 39300102, 2024). "Administering platinum NPs to transient middle cerebral artery occlusion (tMCAO) mice significantly decreased the infarct volume, matrix metalloproteinase-9 (MMP-9) activation, and the generation of superoxide anions (•O2−)." (PMID 38633767, 2024). "To further verify the role of MMP2 and MMP9 in pulmonary ischemia–reperfusion injury, we collected lung tissues from a mouse lung IR model for H&E staining and assessed the extent of lung injury by pathological injury scoring." (PMID 35705936, 2022). "Inhalation of hydrogen gas decreased oxidative stress, exerted neuroprotective effects, and reduced hemorrhagic transformation via reduction in MMP-9 activation in a rat middle cerebral artery occlusion model." (PMID 25925889, 2015). "However, as we found that the concentration of MMP-9 is related to age and gender of the individual, in order to perform an accurate analysis in relation to the colorectal pathologies we corrected the MMP-9 levels for these confounders, as detailed in the Methods section." (PMID 26264519, 2015). "Metformin has been shown to protect the BBB in a mouse model of middle cerebral artery occlusion by downregulating the JNK pathway, reducing MMP-9 expression, and preserving the tight junction protein ZO-1, ultimately reducing infarct size." (PMID 40284474, 2025). "In summary, these data demonstrated that MMP-2 and MMP-9 correlate with worse outcomes in colorectal patients and that MnTE-2-PyP inhibits the expression of MMP-2 and MMP-9 induced by TGF-β." (PMID 30931081, 2019).
retinopathy (20 papers, 2009 to 2025). "The expression and activation of matrix metalloproteinase-9 (MMP-9) has previously been observed in retinopathies, and this effect is directly associated with an increase in GFAP expression." (PMID 28112220, 2017). "In fact, also the current study showed a significant association between plasma MMP-9 levels and the presence of non-proliferative retinopathy in the crude model [standardized β = 0.22 (0.00;0.44)], but this was attenuated after adjustment for confounding." (PMID 25848912, 2015). "The current study is focused on comparing the serum ADAM9 and MMP9 levels of patients with DR and healthy individuals, since their effects on cell destruction, proliferation, and many other retinopathies are similar." (PMID 40943358, 2025). "Our assumption that EMMPRIN, VEGF, and MMP-9 contribute to the development of diabetic microvascular complications such as retinopathy is further supported by the evidence of elevated serum levels of EMMPRIN in diabetic patients." (PMID 38672062, 2024). "A bioinformatics analysis revealed promising MMP9 and APP/Aβ partners for further scrutiny, many of which are already linked with retinopathy." (PMID 36498929, 2022). "In STZ-induced rats, quercetin improved retinopathy by down-regulating matrix metalloproteinase-9 (MMP-9), monocyte chemo-attractant protein-1 (MCP-1), and vascular endothelial growth factor (VEGF)." (PMID 36013325, 2022). "High levels of MMP-9 in models of retinopathy upregulate the expression of VEGF to promote retinal neovascularization." (PMID 34987460, 2021). "Some of them suggest that increased levels of MMP-9 have a stimulating effect on the formation of new blood vessels in cornea while others indicate that low collagenase activity and increased collagen production may be an early and sensitive indicator of a high risk of proliferative retinopathy." (PMID 33218057, 2020). "The activation of MMP-9 has been demonstrated to contribute to the development of retinopathy by increasing vascular permeability and enhancing apoptosis of retinal capillary cells." (PMID 26692905, 2015). "A study based on type 1 diabetic patients showed that peripheral blood MMP-9 levels might serve as surrogate biomarkers of retinopathy in type 1 diabetic patients free of other vascular complications." (PMID 39877847, 2024). "Inhibition of MMP-9 could have a role in the treatment of retinopathy." (PMID 38932813, 2024). "Also, the use of MMP-9 as a surrogate marker for retinopathy has been suggested." (PMID 19758433, 2009). "Other interacting partners of MMP9 included fellow members of the MMP family such as MMP1, -2, -3 and -14, where links with retinopathies have already been discussed." (PMID 36498929, 2022). "Matrix metalloproteinase-9 (MMP9) and total amyloid-beta (Aβ) are prospective biomarkers of ocular ageing and retinopathy." (PMID 36498929, 2022). "Lipocalin 2 (LCN2 or NGAL), alone or complexed with MMP-9 (NGAL/MMP-9), is increased in several retinal disorders." (PMID 33214636, 2020). "The notable variation in the MMP9 marker in the proliferative stage, as opposed to its stability in the non-proliferative stage, suggests a distinct role in retinopathy staging." (PMID 40943358, 2025). "In summary, we report that immature/active MMP9 and total Aβ concentrations across the lifecourse in control subjects and in a subset of AMD patients showed variable levels, which were unrelated to increasing age or retinopathy." (PMID 36498929, 2022). "Elevated circulating levels of MMP-2 and MMP-9 along with elevated levels of TIMP-1 were observed in patients with DR compared to diabetic patients without retinopathy." (PMID 34069322, 2021).
bacterial infection (18 papers, 2008 to 2025). "The upregulation of pro-inflammatory cytokines, including CXCL8, CXCL10, IL-1β, IL-6 and MMP9 was associated with the progression of host bacterial infection." (PMID 40839565, 2025). "This strongly suggests that increased expression of MMP-9 by macrophages is a direct response to bacterial infection." (PMID 38398037, 2024). "When skin injury occurs, a mass of neutrophils will be mobilized to the site of injury, which release cytokines like MMP-8, MMP-9, and ROS to resist bacterial infection as well as modulate thrombus formation." (PMID 36875064, 2023). "As shown by recent studies on Salmonella typhimurium and other pathogens in zebrafish, we confirm here that transcriptional up-regulation of mmp9 upon bacterial infections in fish is a general mechanism." (PMID 22720048, 2012). "The role of increased MMP-8 and MMP-9 concentrations and activity in bacterial infection of the lung is, in contrast to chronic disease, under debate." (PMID 18700005, 2008). "Meanwhile, the high-level stimulations of MMP3 and MMP9 in old hGFs subjected to bacterial infection may reflect a stress-induced aging phenotype in the gingiva." (PMID 27391467, 2016). "In summary, we observed that mmp9 transgene expression correlates with a high maturation grade in neutrophils with increased effector functions, such as recruitment and phagocytosis during bacterial infections and augmented interactions with pre-neoplastic cells." (PMID 38413586, 2024). "In diabetic dermis, the upregulation of CTSG, MMP9, and MMP1 may depend on bacterial infection at the site of DFU and on a dysregulation of growth factors." (PMID 31315286, 2019).
psychiatric disorder (15 papers, 2015 to 2025). A disorder characterized by behavioral and/or psychological abnormalities, often accompanied by physical symptoms. "In conclusion, adolescent psychiatric disorder diagnoses were associated with elevated levels of MMP-9, IL-6, and CRP and with inhibitory control dysfunction." (PMID 40219625, 2025). "MMP-9 is an ECM protein that has been increasingly implicated in psychiatric disorders, including PTSD." (PMID 37333909, 2023). "Dysregulation of MMP-9 levels and activity has been increasingly linked to neurodevelopmental and psychiatric disorders characterized by abnormal brain development." (PMID 37927954, 2023). "A pathogenic influence of MMP-9-1562C/T SNP was observed both in neurological and psychiatric disorders." (PMID 37206663, 2023). "While the regulation of MMP-9 is important for many aspects of normal CNS development and plasticity, misregulation of MMP-9 levels and activity is increasingly implicated in neurodevelopmental and psychiatric disorders that are associated with aberrant brain development." (PMID 26283917, 2015).
infectious disease (13 papers, 2011 to 2024). A disorder directly resulting from the presence and activity of a microbial, viral, or parasitic agent in humans. "Despite studies identifying EVs as significant players in the infectious disease setting, little is known about EV-associated ECM remodeling enzymes, and EV-associated MMP-9 in particular, in infectious diseases and the role that they play." (PMID 38398037, 2024). "Matrix metalloproteinase (MMP)-2 and MMP-9, collectively known as the gelatinases, are closely associated with inflammatory and infectious diseases in a number of organs." (PMID 25523514, 2015). "However, dysregulated MMP-9 expression and activity in infectious diseases can cause significant tissue damage." (PMID 38398037, 2024). "The role of MMP-9 in infectious diseases is particularly interesting and highlights the dual nature of these proteases." (PMID 38398037, 2024). "MMP9 is normally only present at low levels in the brain tissue and cerebrospinal fluid but is markedly upregulated in many infectious diseases of the CNS32." (PMID 30228270, 2018). "Soluble CD40 ligand (sCD40L) and matrix metalloproteinase 9 (MMP-9) are inflammation markers and have been poorly described in infectious disease." (PMID 23870715, 2013). "One explanation would be that, in the context of infectious disease, neutrophils MMP-9 and -8 can be released immediately after stimulation, whereas the others required a longer process of increase gene transcription to drive secretion." (PMID 21533198, 2011). "MMP9 was identified to be significant in various diseases, particularly in infectious diseases." (PMID 32595353, 2020). "Elevated levels of MMP-9 were found in different inflammatory and infectious diseases." (PMID 25931987, 2015). "We measured the levels of MMP-8, MMP-9 and TIMP-1 by specific immunoassays previously found to be suitable for diagnosis and monitoring of systemic low-grade inflammation associated with cardiovascular and infectious diseases as well as other inflammatory states." (PMID 28407807, 2017).